MIR539 (microRNA 539)
Synonyms: hsa-mir-539; MIRN539; mir-539
Gene: MicroRNA gene on chromosome 14 (101,047,321 to 101,047,398, forward strand). Ensembl gene ENSG00000202560.
Gene Ontology:
Biological process: miRNA-mediated post-transcriptional gene silencing
Cellular component: RISC complex
Homologues: Orthologues: chimpanzee ptr-mir-539 (100% identical), guinea pig MIR539 (94% identical). Paralogues in human: MIR494 (81% identical), MIR487A (79% identical), MIR382 (77% identical), MIR154 (74% identical), MIR1185-1 (72% identical), MIR377 (71% identical), MIR496 (71% identical), MIR1185-2 (69% identical), MIR381 (69% identical), MIR487B (69% identical), MIR323B (64% identical), MIR323A (63% identical), and 4 more.
Diseases named in the same sentence as MIR539 in open-access papers:
MIR539 is named in the same sentence as 4 diseases in open-access papers, as found by Europe PMC text mining. Sharing a sentence is not in itself a finding about the gene and the disease. The quoted sentences say what the papers report.
breast carcinoma (1 paper, 2024). "In patients with breast cancer, decreased expression of MIR539 was significantly associated with lymph node metastasis." (PMID 39145770, 2024). "In breast cancer cells, overexpression of MIR539 inhibited the proliferation and promoted apoptosis of breast cancer cells, suppressed EMT, and sensitized cells to cisplatin treatment." (PMID 39145770, 2024). "Previous reports indicate that MIR539 expression is downregulated in breast cancer tissues and cell lines, and MIR539 acts as a tumor suppressor by targeting epidermal growth factor receptor, specificity protein 1, or laminin subunit alpha 4 expression." (PMID 39145770, 2024).
leukaemia (1 paper, 2015). "Interestingly, the MIR539 gene is located in the DLK1-DIO3 imprinting region that contains a microRNA cluster involved in leukaemia pathogenesis." (PMID 26444494, 2015).
MIR539 also shares sentences with these, for which no sentence is quoted: lymph node metastasis (1 paper); tumor (1).